LINC02004 (long independently transcribed non-coding RNA 2004)
Gene: Long non-coding RNA gene on chromosome 3 (134,312,144 to 134,341,848, forward strand). Ensembl gene ENSG00000240006.
Diseases named in the same sentence as LINC02004 in open-access papers:
LINC02004 is named in the same sentence as 2 diseases in open-access papers, as found by Europe PMC text mining. Sharing a sentence is not in itself a finding about the gene and the disease. The quoted sentences say what the papers report.
bladder cancer (1 paper, 2022). "Among them, LINC02004 is unfavorable to the prognosis of bladder cancer." (PMID 35280814, 2022).
pancreatic cancer (1 paper, 2024). "We found that LINC00519 and LINC02004 were highly expressed in pancreatic cancer cell lines, while PAN3-AS1 was lowly expressed." (PMID 39872533, 2024).